SLC23A2 (solute carrier family 23 member 2)
Description:
Sodium/ascorbate cotransporter. Mediates electrogenic uptake of vitamin C, with a stoichiometry of 2 Na(+) for each ascorbate.
Synonyms: KIAA0238; NBTL1; SLC23A1; SVCT2; YSPL2
Tractability: Antibody: UniProt places it where antibodies can reach, with high confidence; its Gene Ontology location is reachable by antibodies, with high confidence; UniProt predicts a signal peptide or a membrane-spanning region. PROTAC: ubiquitination databases record sites on it; its protein half-life has been measured.
Target class: Electrochemical transporter; SLC23 family of ascorbic acid transporters; Transporter; SLC superfamily of solute carriers
Gene: Protein-coding gene on chromosome 20 (4,851,729 to 5,010,293, reverse strand). Ensembl gene ENSG00000089057.
Subcellular location: Cell membrane
Subcellular location (Human Protein Atlas): Vesicles; Golgi apparatus
Pathways (Reactome):
Metabolism: Vitamin C (ascorbate) metabolism
Gene Ontology:
Molecular function: L-ascorbate:sodium symporter activity; L-ascorbic acid transmembrane transporter activity; protein binding; transmembrane transporter activity
Biological process: L-ascorbic acid transmembrane transport; L-ascorbic acid metabolic process; cellular response to ethanol; positive regulation of dendrite extension; response to oxidative stress; transmembrane transport
Cellular component: apical plasma membrane; basolateral plasma membrane; plasma membrane; membrane; basal plasma membrane; cytoplasm
Genetic constraint (gnomAD): Loss-of-function variants: 21 observed, 41.98 expected, observed/expected ratio (o/e) 0.5, 90% interval 0.35 to 0.72. The upper end of that interval is the gene's LOEUF score, 0.72, which puts it in group 2 of 6, group 1 being the genes least tolerant of losing a copy. Missense variants: 359 observed, 617.44 expected, observed/expected ratio (o/e) 0.58, 90% interval 0.53 to 0.63. Synonymous variants: 241 observed, 246.77 expected, observed/expected ratio (o/e) 0.98, 90% interval 0.88 to 1.09.
Homologues: Orthologues: chimpanzee SLC23A2 (100% identical), macaque SLC23A2 (100% identical), dog SLC23A2 (98% identical), guinea pig SLC23A2 (98% identical), pig SLC23A2 (98% identical), rabbit SLC23A2 (95% identical), mouse Slc23a2 (95% identical), rat Slc23a2 (95% identical), tropical clawed frog slc23a2 (88% identical), zebrafish slc23a2 (79% identical), Drosophila melanogaster CG6293 (38% identical). Paralogues in human: SLC23A1 (58% identical), SLC23A3 (26% identical).
Diseases named in the same sentence as SLC23A2 in open-access papers:
SLC23A2 is named in the same sentence as 52 diseases in open-access papers, as found by Europe PMC text mining. Sharing a sentence is not in itself a finding about the gene and the disease. The quoted sentences say what the papers report.
breast carcinoma (14 papers, 2017 to 2025). "Interestingly, we found higher mRNA expression of vitamin C transporters (SLC23A1 and SLC23A2) in breast cancer patients in comparison to control samples." (PMID 38499584, 2024). "Moreover, mRNA expression of SLC23A1 and SLC23A2 was elevated in leukocytes from breast cancer patients." (PMID 38499584, 2024). "Moreover, the ascorbate level in the plasma of breast cancer patients was decreased with the accompanying increase of sodium-dependent vitamin C transporters (SLC23A1 and SLC23A2)." (PMID 38499584, 2024).
diabetes (4 papers, 2014 to 2025). "The differential expression profile of solute carrier family 23 member 2 (SLC23A2) gene was seen in diabetics versus the CG (p = 0.001), and in T2DM + DR versus T2DM − DR (p < 0.05)." (PMID 33182408, 2020).
gastric cancer (4 papers, 2017 to 2022). A primary or metastatic malignant neoplasm involving the stomach. "SLC23A2(SVCT2), which takes the function to reduce the oxidative damage caused by copper overloaded, was reported to be a polymorphism in gastric cancer or chronic lymphocytic leukemia." (PMID 35995782, 2022). "Expression of the solute carrier family 23 member 2 (SLC23A2) has been shown to be a colon and gastric cancer biomarker." (PMID 28450890, 2017). "However, polymorphisms of the second vitamin C transporter SVCT2: SLC23A2 (SLC23A2 rs6116568 and SLC23A2 rs12479919) were correlated with gastric cancer incidence." (PMID 33352824, 2020). "Another study showed SLC23A2 polymorphism was associated with gastric cancer but SLC23A1 polymorphism was not." (PMID 32899442, 2020).
brain hemorrhage (3 papers, 2011 to 2024). "However, the pivotal role of SVCT2 in the brain remains undisputed as supported by convincing studies in Slc23a2 knockout mice that display severe brain hemorrhage and high perinatal mortality." (PMID 31601028, 2019).
colon carcinoma (2 papers, 2013 to 2023). "A colon carcinoma cell line exhibiting resistance to 5-FU has been reported to show lower expression of SLC23A2 mRNA than its parent cells." (PMID 23420099, 2013).
acute coronary syndrome (1 paper, 2013). Signs and symptoms related to acute ischemia of the myocardium secondary to coronary artery disease. "Hazard ratio of acute coronary syndrome according to SLC23A2 genotype in the Danish Diet, Cancer and Health Cohort." (PMID 23990905, 2013). "Hazard ratio of acute coronary syndrome according to SLC23A2 genotype and dietary vitamin C intake." (PMID 23990905, 2013).
cognitive decline (1 paper, 2021). "Results of association analysis of three functional variants of SLC2A1 and SLC23A2 with cognitive decline (MCI or dementia)." (PMID 34780525, 2021). "In the present study, we aimed to examine the effects of functional variants of VC transporter genes expressed in the brain (SLC2A1, SLC2A3, and SLC23A2) on APOE4-associated risk of developing cognitive decline." (PMID 34780525, 2021). "The results showed that the functional variants of SLC2A1 and SLC23A2 may affect or modify the risk of developing APOE4-associated cognitive decline." (PMID 34780525, 2021). "Whether the rs1279683 genotype in SLC23A2 changes the VC level in the human brain is unclear, and differences in brain SLC23A2 expression might be the reason for susceptibility to cognitive decline in this study." (PMID 34780525, 2021). "This case–control study involved the Japanese cohort population to determine the association between VC transporter genes (SLC23A2, SLC2A1, and SLC2A3) and APOE4-associated risk of developing cognitive decline (MCI or dementia)." (PMID 34780525, 2021). "To investigate the relationship between cognitive decline and brain VC level in humans, we need to focus on the roles of brain-expressed VC transporters (SLC23A2, SLC2A1, and SLC2A3) in human cognitive function." (PMID 34780525, 2021). "Contrary to SLC23A2, in the stratified analysis by genotype in SLC2A1, APOE4 was shown to have a significant risk of cognitive decline in the high expression groups of SLC2A1 (rs710218 and rs841851), but not in the low expression groups." (PMID 34780525, 2021). "For this purpose, we found three functional SNVs associated with the changes in SLC2A1 and SLC23A2 expression by searching several publicly available databases, and analyzed the effects of these variants on APOE4-associated risk of developing cognitive decline." (PMID 34780525, 2021). "We hypothesized that genetic variants of VC transporters (SLC23A2, SLC2A1, and SLC2A3) expressed in the brain could affect the risk of developing APOE4-associated cognitive decline." (PMID 34780525, 2021). "As for SLC23A2, in the stratified analysis by genotype, APOE4 had a significant risk of cognitive decline in the low expression group of rs1279683, but not in the high expression group." (PMID 34780525, 2021).
esophageal carcinoma (1 paper, 2023). A primary or metastatic malignant neoplasm involving the esophagus. "Moreover, some CRGs, including PIH1D2, SLC23A2, SLC25A5, ATP7A, PDHX and COX7B, were reported to be tightly linked with the grading and immune infiltration of esophageal carcinoma." (PMID 37380924, 2023).
follicular lymphoma (1 paper, 2020). Follicular lymphoma is a form of non-Hodgkin lymphoma characterized by a proliferation of B cells whose nodular structure of follicular architecture is preserved. "An elevated risk of follicular lymphoma was also associated with a genetic variant of SVCT2 (SLC23A2 rs1776948)." (PMID 33352824, 2020).
lymphoma (1 paper, 2008). A malignant (clonal) proliferation of B- lymphocytes or T- lymphocytes which involves the lymph nodes, bone marrow and/or extranodal sites. "Other associations were observed between risk of lymphoma subtypes and SLC23A1, SLC23A2, and MMP9 SNPs." (PMID 18636124, 2008). "By extension, if the variant C allele results in lower SLC23A2 expression, then the increased NHL risk associated with the variant C allele might suggest that reduced vitamin C bioavailability increases lymphoma risk." (PMID 18636124, 2008). "Thus, the influence of SLC23A1 and SLC23A2 genetic variation on NHL risk suggests that both vitamin C uptake and storage may be involved in the pathogenesis of lymphoma." (PMID 18636124, 2008).
squamous cell carcinoma of the (1 paper, 2014). "However, the association between the SLC23A2-05 variation and positive HPV, as a risk factor for squamous cell carcinoma of the head and neck, is ambiguous." (PMID 24932237, 2014). "The results of the present study demonstrate that the SLC23A2-05 and KRAS-LCS6 polymorphisms are not a risk factor for squamous cell carcinoma of the head and neck." (PMID 24932237, 2014).
squamous cell carcinoma of the head and neck (1 paper, 2014). "In conclusion, in the present study, squamous cell carcinoma of the head and neck was highly affected by environmental factors when compared with the affect of SLC23A2-05 and KRAS-LCS6 polymorphisms." (PMID 24932237, 2014).
cancer (23 papers, 2011 to 2025). A tumor composed of atypical neoplastic, often pleomorphic cells that invade other tissues. "SLC23A2 (solute carrier family 23 member 2) was known to be required for sodium-dependent transporters of vitamin C, and several types of cancer were reported to be linked with a deficiency in vitamin C." (PMID 35807355, 2022). "The association of the KRAS-LCS6 and SLC23A2-05 polymorphisms with cancer presence is demonstrated in Table III and in Table IV, the correlation between the two polymorphs and TNM staging is shown; P>0.05 for all values." (PMID 24932237, 2014). "Among G allele patients with the SLC23A2-05 polymorphism, the cancer risk in association with HPV16 was 5.0 (95% CI, 3.2–7.8)." (PMID 24932237, 2014). "In Table II, the association between the KRAS-LCS6 and SLC23A2-05 polymorphisms, and the degree of cancer differentiation (KRAS-LCS6, P=0.140; and SLC23A2-05, P=0.186) and cancer location (KRAS-LCS6, P=0.640; and SLC23A2-05, P=0.447) is shown." (PMID 24932237, 2014). "On the other hand, genetic variations in the vitamin C transporter SLC23A2 have been associated with several types of cancer, supporting the relevance of this gene in antioxidant mechanisms." (PMID 22171153, 2011). "In determining if the genotype modifies the interaction between citrus consumption, HPV16 and cancer risk, there was an increased risk of cancer found in individuals with one G allele to SLC23A2-5 polymorphism, HPV16 seropositive and high citrus consumption (OR, 7.4; 95% CI, 3.6–15.1)." (PMID 24932237, 2014). "The SLC23A2-05 polymorphism plus HPV16 infection were considered to be a risk factor for cancer." (PMID 24932237, 2014). "The association of SLC23A2 with GABRB1 indicates potential interactions related to amino acid transport and neurotransmission in cancer cells." (PMID 39267843, 2024). "The MDR program analysis did not identify any statistically significant association between cancer and the KRAS-LCS6 and SLC23A2-05 polymorphisms (ratio, 0.7174; testing balanced accuracy, 0.5157; P=0.4090)." (PMID 24932237, 2014). "However, incidence of this cancer was correlated with two genetic variations of SVCT2, SLC23A2 rs4987219 and SLC23A2 rs1110277." (PMID 33352824, 2020).
tumor (12 papers, 2017 to 2026). "Correlations of SLC23A2 gene polymorphisms related to ascorbate levels and disease risks depend on tumor entity and study population." (PMID 37107291, 2023). "Additionally, the overexpression of ADA and SLC23A2 in tumor tissues suggests that these genes could be interesting therapeutic targets." (PMID 39267843, 2024).
cardiovascular disease (1 paper, 2013). "However, this may be the first time that genetic variation in the vitamin C transporter gene SLC23A2 is tested in relation to cardiovascular disease, hence the results require replication." (PMID 23990905, 2013).
intestinal diseases (1 paper, 2023). "Several of these genes, including Ralbp1, Pfas, Tyro3, Opcml, Syne2, Six4, Tll2, and Slc23a2, were previously implicated in gut microbiome abundance, metabolic traits, and several intestinal diseases." (PMID 37420306, 2023).
SLC23A2 also shares sentences with these, for which no sentence is quoted: colorectal cancer (4 papers); neuroblastoma (4); Alzheimer disease (3); Cerebral ischemia (3); glioblastoma (3); ischemia (3); glaucoma (2); glioma (2); hepatocellular carcinoma (2); liver cancer (2); respiratory failure (2); Stroke (2); bipolar disorder (1); bladder cancer (1); brain injury (1); breast tumors (1); cholangiocarcinoma (1); chronic lymphocytic leukemia (1); dementia (1); embryonal carcinoma (1); Huntington disease (1); Hypernatremia (1); infection (1); intrauterine growth restriction (1); melanoma (1); metastatic melanoma (1); Obesity (1); oligodendroglioma (1); osteoarthritis (1); ovarian carcinoma (1).
A further 6 diseases each share a sentence with SLC23A2 in 1 paper.